RLN2 (relaxin 2)
Diseases named in the same sentence as RLN2 in open-access papers (continued):
Sharing a sentence is not in itself a finding about the gene and the disease.
essential hypertension (2 papers, 2022 to 2023). Hypertension that presents without an identifiable cause. "Associations between rs72499174 from RLN2 and two phenotypes–hypertension (q = 0.0355) and hypertriglyceridaemia (q = 0.0704)–were the two closest to the significance cut-offs used." (PMID 37967073, 2023). "The myriad cardiovascular properties of relaxin-2 could potentially prevent some pathophysiological mechanisms that cause target organ damage during hypertension." (PMID 35887517, 2022). "During masked hypertension, relaxin-2 levels seems to be lower when compared with white coat hypertension (in which organ damage and cardiovascular events are less prevalent compared with essential hypertension)." (PMID 35887517, 2022). "It has been described that during the presence of CVDs (such as HF, AF, ischemic heart disease, MI, aortic valve disease, hypertension, and atherosclerosis) endogenous relaxin-2 levels suffer significant variations." (PMID 35887517, 2022). "In the following subsections, we will focus on the most relevant studies regarding relaxin-2 circulatory levels in different backgrounds of CVDs, especially in HF, AF, ischemic heart disease, MI, aortic valve disease, hypertension, and atherosclerosis." (PMID 35887517, 2022). "Moreover, future works should evaluate relaxin-2 plasma levels in patients with CAVS-induced hypertension and with non-CAVS-related hypertension since this syndrome constitutes a known risk factor for CAVS and the calcification of the aortic valve could lead to the development of hypertension." (PMID 35887517, 2022). "However, these possibilities notwithstanding, the specific role of endogenous relaxin-2 on hypertensive cardiovascular damage is not fully deciphered, although some authors have studied plasmatic levels of this hormone in patients with hypertension." (PMID 35887517, 2022).
fibrosis (2 papers, 2020 to 2026). the formation of excess fibrous connective tissue in an organ or tissue in a reparative or reactive process. "The human genome contains three relaxin genes, among which relaxin-2 (RLN2) shares similar antifibrosis effects with mouse relaxin-1 (RLN1) in murine fibrosis models, allowing early-stage development of human relaxin-based drugs to be tested in mouse models." (PMID 41552388, 2026).
metastatic disease (2 papers, 2014 to 2025). "Kruskal–Wallis and post-hoc testing found that YKL-40 and CEA were associated with tumor progression, but RLN2 and CA 19-9 were increased primarily in advanced, metastatic disease." (PMID 41373753, 2025).
preeclampsia (2 papers, 2021 to 2025). Preeclampsia is a hypertensive disorder of pregnancy that is characterized by new-onset hypertension with proteinuria presenting after 20 weeks of gestation, and depending on mild or severe forms may initially present with severe headache, visual disturbances, and hyperreflexia. "By inhibiting neutrophil activation, relaxin-2 may help regulate maternal immune responses, suggesting a potential role in early pregnancy processes relevant to preeclampsia, a disorder associated with excessive inflammation." (PMID 41196672, 2025).
renal fibrosis (2 papers, 2023 to 2025). A final common manifestation of a wide variety of chronic kidney diseases characterized by glomerulosclerosis and tubulointerstitial fibrosis. "Our study examined whether delivery of relaxin-2 mRNA to kidney cells in vitro and in vivo could inhibit mechanisms leading to renal fibrosis." (PMID 37545557, 2023). "Since there are currently no specific therapies for renal fibrosis, we explored whether inducing local production of the anti-fibrotic molecule relaxin-2 in kidney cells has potential as a strategy for suppressing the development of renal fibrosis." (PMID 37545557, 2023).
thyroid cancer (2 papers, 2015 to 2022). "RXFP1 mediated the motility-enhancing effect of RLN2 via induction of S100A4 in human thyroid carcinoma cells and RLN2 enhanced thyroid xenograft angiogenesis." (PMID 26322020, 2015). "RLN2/RXFP1 signaling promotes thyroid cancer motility and invasiveness." (PMID 26322020, 2015). "Increased expression of RLN2 and RXFP1 was also shown in thyroid cancer." (PMID 26322020, 2015).
aortic valve disease (1 paper, 2022). "However, there exists a necessity of further studies to unravel the specific influence of relaxin-2 on aortic valve disease, for example, determining the expression of relaxin-2 in the healthy valve or analysing the changes in circulatory relaxin-2 levels after aortic valve replacement." (PMID 35887517, 2022).
aortic valve stenosis (1 paper, 2022). Aortic valve stenosis (AVS) is a condition characterized by narrowing of the heart's aortic valve opening. "In another work with patients with severe aortic valve stenosis (AVS) with and without HF, plasmatic relaxin-2 did not change in HF, and it seemed to be independent of the presence, type, or severity of HF." (PMID 35887517, 2022).
atherosclerosis (1 paper, 2022). A disease characterized by the build-up of fatty material and calcium deposition in the arterial wall resulting in partial or complete occlusion of the arterial lumen. "Interestingly, relaxin-2 exerts an anti-inflammatory effect by decreasing IL-6 mRNA expression and plasma levels in rat left ventricle and infarcted myocardium as well as in apolipoprotein E-deficient mice model of atherosclerosis." (PMID 35887517, 2022). "Tissue relaxin-2 mRNA levels are inversely correlated with MMP-2 in mild atherosclerosis and positively correlated with eNOS in moderate atherosclerosis, which supports the beneficial effect of relaxin-2 in this pathology." (PMID 35887517, 2022). "Those insights could indicate that relaxin-2 acts as a compensatory response during the reduction in blood supply in the early stages of atherosclerosis, a mechanism that presumably becomes ameliorated in the late clinical stages of the disease." (PMID 35887517, 2022). "A feasible explanation of these results could be that some confounders, such as insulin sensitivity, may modify the relationship between relaxin-2 and atherosclerosis in diabetes." (PMID 35887517, 2022). "Serum levels of relaxin-2 are higher in the early stages of atherosclerosis and gradually decrease with the progression of the disease, eventually showing comparable results between patients with permanent ischemic manifestations from target organs and healthy subjects." (PMID 35887517, 2022). "In this context, it is conceivable to hypothesize that relaxin-2 may be involved in several vascular diseases such as atherosclerosis, despite the lack of recent reports deciphering the specific role of relaxin-2 during the atherosclerotic process." (PMID 35887517, 2022).
biliary tract cancer (1 paper, 2025). "Therefore, this study assessed the roles of stromal barriers in regulating CAR-T cell delivery to cancer cells and the potential of RLN2 expression and secretion by CAR-T cells for enhancing antitumor efficacy in pancreatic and biliary tract cancers." (PMID 40666525, 2025).
colitis (1 paper, 2025). Inflammation of the colon. "Studies have demonstrated that RLN2 expression is downregulated in colitis models and negatively correlates with the severity of intestinal inflammation." (PMID 40529132, 2025).
endometrioid endometrial carcinoma (1 paper, 2018). "We then examined RLN2 and RXFP1 expression in 80 human endometrioid endometrial carcinoma tissues." (PMID 30126180, 2018). "Furthermore, the significance of RLN2 and RXFP1 was examined by immunohistochemistry in 80 cases of endometrioid endometrial carcinoma (EEC) tissues." (PMID 30126180, 2018).
endothelial dysfunction (1 paper, 2022). In vascular diseases, endothelial dysfunction is a systemic pathological state of the endothelium (the inner lining of blood vessels) and can be broadly defined as an imbalance between vasodilating and vasoconstricting substances produced by (or acting on) the endothelium. "These outcomes suggest that relaxin-2 improves endothelial dysfunction and functions as a natural and potent therapeutic vasoprotector." (PMID 35887517, 2022).
germinal matrix hemorrhage (1 paper, 2020). "Our aim of the study is to investigate the effects of rh-relaxin-2 on mast cells and the underlying mechanisms in a germinal matrix hemorrhage (GMH) rat model." (PMID 32859236, 2020).
Hydrocephalus (1 paper, 2020). Hydrocephalus is an active distension of the ventricular system of the brain resulting from inadequate passage of CSF from its point of production within the cerebral ventricles to its point of absorption into the systemic circulation. "Our findings showed that rh-relaxin-2 attenuated degranulation of mast cells and neuroinflammation, improved neurological outcomes, and ameliorated hydrocephalus after GMH through RXFP1/PI3K-AKT/TNFAIP3/NF-κB signaling pathway." (PMID 32859236, 2020).
ischemic heart disease (1 paper, 2022). "At present, there exists evidence to sustain the hypothesis that the hormone relaxin-2 could counteract many physiopathologic mechanisms which take place in ischemic heart disease." (PMID 35887517, 2022). "Considering all this evidence, we would expect that endogenous relaxin-2 could be a relevant biomarker during clinical daily practice for the prevention of ischemic heart disease." (PMID 35887517, 2022). "Interestingly, these studies bring up the question of whether relaxin-2, in addition to its ability as a preventative drug that induces cardioprotection during I/R injury, could also be considered a useful biomarker for the prevention and diagnosis in advance of ischemic heart disease." (PMID 35887517, 2022).
ovarian carcinoma (1 paper, 2024). A malignant neoplasm originating from the surface ovarian epithelium. "The prognostic impact of PGRMC1 is largely unexplored in ovarian cancer, but high serum-levels of relaxin-2 have been associated with tumor progression and adverse survival in several malignancies, including ovarian cancer." (PMID 38578428, 2024).
pancreatic cancer (1 paper, 2025). "We sought to further evaluate the therapeutic potential of RLN2-secreting CAR-T cells in models that more closely recapitulate the stromal-rich tumor microenvironment encountered in human pancreatic cancer." (PMID 40666525, 2025). "We examined the effect of RLN2 on pancreatic stellate cells—considered major contributors to the desmoplastic reaction in human pancreatic cancer." (PMID 40666525, 2025). "In pancreatic stellate cells, the major sources of CAFs in pancreatic cancer, RLN2 induced MMP-1 and MMP-7 expression." (PMID 40666525, 2025). "Accordingly, we screened for models characterized with stroma vessel type tumors and identified two human pancreatic cancer cell lines, Capan-1 and BxPC-3, both of which exhibited high CD44v6 expression and detectable LGR7 expression, the cognate receptor for RLN2." (PMID 40666525, 2025).
portal hypertension (1 paper, 2020). Increased blood pressure in the portal venous system. "In preclinical models, recombinant human relaxin-2 (serelaxin) had anti-fibrotic effects and ameliorated portal hypertension (PH)." (PMID 32164767, 2020).
pulmonary hypertension (1 paper, 2022). Increased pressure within the pulmonary circulation due to lung or heart disorder. "During AHF, serum relaxin-2 concentration at admission was associated with pulmonary hypertension and right heart overload." (PMID 35887517, 2022). "When comparing pulmonary arterial hypertension (PAH) and HF with preserved EF (HFpEF)-induced pulmonary hypertension or with HFpEF alone, serum relaxin-2 levels were significantly augmented in the group of patients with PAH." (PMID 35887517, 2022).
spinal cord injury (1 paper, 2025). Penetrating and non-penetrating injuries to the spinal cord resulting from traumatic external forces (e.g., WOUNDS, GUNSHOT; WHIPLASH INJURIES; etc.). "This study aims to assess the therapeutic effectiveness of Relaxin‐2 (RLN‐2) in promoting functional recovery and neuroprotection following spinal cord injury (SCI) in mice." (PMID 40392018, 2025).
tumor (20 papers, 2008 to 2025). "Within the myeloid lineage, RLN-2 modulates macrophage infiltration and shapes the tumor microenvironment by increasing tumor-associated macrophages." (PMID 41196672, 2025). "In this study, we focused on the MMP-inducing effects of RLN2 and the associated collagen degradation using a subcutaneous xenograft tumor model in immunodeficient NSG mice." (PMID 40666525, 2025). "Several studies indicate that RLN-2 promotes the differentiation of infiltrating monocytes into tumor-associated macrophages (TAMs), cells known to support tumor progression by stimulating angiogenesis, immune evasion, and metastasis." (PMID 41196672, 2025). "The activation of the G protein‐coupled receptor RXFP1 by RLN2 or CTRP8 has been associated with enhanced tumor cell motility and tissue invasion in several tumors, but the underlying molecular mechanisms remain poorly understood." (PMID 33960104, 2022). "This was associated with induction of high relaxin-2 serum levels, strongly suggesting a tumour-promoting effect of relaxin-2 either directly on the tumour cells or via the microenvironment." (PMID 23963762, 2014). "However, based on the received post-hoc results, it is probable that only YKL-40 and CEA levels are associated with tumor growth, and RLN2 and CA 19-9 are associated only with advanced stages of cancer, when metastases occur." (PMID 41373753, 2025). "It is therefore plausible that RLN2 acts locally within the tumor niche while remaining below the detection threshold in peripheral circulation." (PMID 41373753, 2025). "RLN2 overexpression has also been reported in other neoplasms such as prostate, thyroid, and endometrial cancers." (PMID 41373753, 2025). "RLN2-secreting CAR-T cells from the blood of donor 1 significantly inhibited tumor growth compared to both conventional CAR-T and Ctrl-T cells." (PMID 40666525, 2025). "We demonstrated the utility of RLN2-secreting CAR-T cell therapy in an SU86.86-derived subcutaneous xenograft tumor model." (PMID 40666525, 2025). "RLN2 is a novel candidate, and preclinical studies show that it can impact the tumor microenvironment, immune cell infiltration, and extracellular matrix remodeling, potentially increasing the efficacy of immunotherapy." (PMID 41373753, 2025). "More recent reports indicate that RLN2 plays a complex, bidirectional role in cancer, exhibiting both pro- and antitumor effects depending on the tumor type." (PMID 41373753, 2025). "On the other hand, there are reports of potential tumor-suppressing effects of RLN2, emphasizing the need for further investigation into its role as a biomarker and potential therapeutic target." (PMID 41373753, 2025). "Collectively, these findings suggest that RLN2 secreted locally by stromal CAR-T cells acts on SU86.86 tumor cells to enhance MMP expression, playing a pivotal role in the therapeutic effect." (PMID 40666525, 2025). "In animal models of CRC, CAR-T with lymphocytes engineered to secrete RLN2 demonstrated enhanced tumor infiltration and superior antitumor activity compared with conventional CAR-T cells." (PMID 41373753, 2025). "Immunofluorescence staining for CD3, used to detect tumor-infiltrating CAR-T cells, demonstrated that RLN2-secreting CAR-T cells were present not only in the stroma but also around the cancer cells within the tumor clusters." (PMID 40666525, 2025). "We evaluated expression of progesterone receptor (PR), progesterone receptor membrane component 1 (PGRMC1), relaxin-2, and transforming growth factor beta 1 (TGFβ1) in tumor tissue from 92 women with HGSC parous (n = 73) and nulliparous (n = 19)." (PMID 38578428, 2024). "Androgen-independent growth of tumor cells can be mediated by the hormone RLN2, which can activate the AR signaling pathway by inducing the formation of the β-catenin–AR complex and its translocation to the nucleus." (PMID 34440475, 2021).
tumor (continued). "Porcine relaxin as well as relaxin-2 was found to influence tumour cell proliferation in a biphasic way regarding time course and concentration." (PMID 23963762, 2014). "A tumour-promoting function of relaxin-2 has been demonstrated also in thyroid cancer where it fosters invasion in vitro via increased invadopodia formation and MMP upregulation as well as xenograft growth in nude mice." (PMID 23963762, 2014). "The number of macroscopic tumor nodules in relaxin-2 siRNA-treated mice was 9.46 ± 1.8 lung nodules per mouse versus 72.4 ± 7.4 nodules in the controls (n = 5 mice/group)." (PMID 23758748, 2013). "When injected subcutaneously in nude mice, all xenograft tumours derived from anti- relaxin-2 mAb treated MG-63 tumors contained reduced or almost undetectable levels of relaxin-2 protein when compared with the control tumour tissues." (PMID 23758748, 2013). "New blood vessel formation was significantly reduced in MG-63 tumor by anti- relaxin-2 mAb in the intervention model (80% inhibition)." (PMID 23758748, 2013). "The results showed the number of macroscopic tumor nodules in relaxin-2 siRNA-treated mice was significantly decreased, and the effects did reach statistical significance." (PMID 23758748, 2013). "The tumors MG-63 cells treated with anti- relaxin-2 mAb for 42 d showed a significant reduction of tumor volum as compared with control groups, whereas MG-63 cells developed obvious tumors in nude mice." (PMID 23758748, 2013). "Downregulation of relaxin-2 by siRNA or anti- relaxin-2 mAb on MG-63 effectively suppressed tumor growth in vitro or vivo through increased apoptosis and decreased proliferation of MG-63 cancer cells." (PMID 23758748, 2013). "Exogenous down regulation of relaxin-2 suppressed proliferation angiogenesis and migration in MG-63 cells and decreased tumor formation, metastasis and angiogenesis in nude mice." (PMID 23758748, 2013). "In vitro assays showed that relaxin-2 siRNA treatment was indeed able to reduce significantly tumor invasiveness." (PMID 23758748, 2013). "Mice with MG-63/ relaxin-2 siRNA cells were sacrificed on the same day of tumor injection (14 days), lungs were harvested and lung sections were examined for cancer cell micrometastasis." (PMID 23758748, 2013). "In vivo, knockdown of relaxin-2 with anti- relaxin-2 mAb treatment inhibited tumor growth by 62% (P < 0.01) and the formation of lung metastases was inhibited by 72.4% (P < 0.01)." (PMID 23758748, 2013). "Consequently, RLN2 facilitates the infiltration of immune cells, including T lymphocytes, into the tumor, thereby disrupting the stromal barrier that impairs the effectiveness of immunotherapy." (PMID 41373753, 2025). "Furthermore, CAR-T cells secreting relaxin-2 demonstrated increased efficacy and infiltration in stromal-rich solid tumors by remodeling the tumor microenvironment and reducing fibrosis, ultimately promoting better T-cell migration and antitumor responses." (PMID 41181132, 2025). "Known for its role in pregnancy, RLN2 facilitates the softening and remodeling of collagen in the cervix and pelvic ligaments, and also promotes collagen degradation in the tumor microenvironment by upregulating matrix metalloproteinase levels by binding to the receptor LGR7/RXFP1." (PMID 40666525, 2025). "While these findings suggest that RLN2 may influence the tumor vasculature, the functional significance of this effect in the context of cancer remains unclear." (PMID 40666525, 2025). "However, experimental evidence suggests that RLN2 plays a significant role in the stroma-rich tumor microenvironment." (PMID 41373753, 2025). "RLN2 may also modulate pathways related to extracellular matrix remodeling, angiogenesis, and apoptosis, influencing tumor growth dynamics and metastatic potential." (PMID 41373753, 2025).